ENSG00000260092 (TMEM231-CHST5 readthrough protein)
Gene: Protein-coding gene on chromosome 16 (75,528,532 to 75,545,428, reverse strand). Ensembl gene ENSG00000260092.
Genetic constraint (gnomAD): Missense variants: 57 observed, 64.36 expected, observed/expected ratio (o/e) 0.89, 90% interval 0.71 to 1.1. Synonymous variants: 29 observed, 26.56 expected, observed/expected ratio (o/e) 1.09, 90% interval 0.81 to 1.49.